GREM1 (gremlin 1, DAN family BMP antagonist)
Diseases named in the same sentence as GREM1 in open-access papers (continued):
Sharing a sentence is not in itself a finding about the gene and the disease.
renal fibrosis (5 papers, 2017 to 2022). A final common manifestation of a wide variety of chronic kidney diseases characterized by glomerulosclerosis and tubulointerstitial fibrosis. "Accordingly, specific deletion of Grem-1 in tubular cells diminished renal fibrosis in folic acid-induced damage in mice." (PMID 30386246, 2018). "In the context of renal fibrosis, tubular epithelial overexpression of Grem1 in mouse models of AKI and DN resulted in increased renal damage and a more severe phenotype." (PMID 28100499, 2017). "Others have suggested that Grem1 can activate VEGFR2 in renal epithelial cells and that this pathway contributes to Grem1-induced renal fibrosis." (PMID 28100499, 2017). "Reductions in the levels of gremlin 1 (GREM1) have also been shown to attenuate diabetic and other forms of renal fibrosis." (PMID 28956186, 2017). "GREM1 increases TGF-β production and activates the Smad signaling pathway in renal fibrosis." (PMID 32141512, 2020). "In addition to the range of studies that support the hypothesis of targeting Grem1 in fibrotic conditions, these data further enhance our understanding of the molecular basis of Grem1-mediated renal damage and contribute to the body of evidence for Grem1 involvement in renal fibrosis." (PMID 28100499, 2017).
bladder cancer (4 papers, 2020 to 2025). "Similarly, in bladder cancer, GREM1 has been shown to drive tumor progression by activating the PI3K/AKT signaling pathway." (PMID 40066442, 2025). "Gremlin-1 (GREM1) is a protein closely related to tumor growth, although its function in bladder cancer (BCa) is currently unknown." (PMID 37605239, 2023).
endometriosis (4 papers, 2023 to 2025). The growth of functional endometrial tissue in anatomic sites outside the uterine body. "Through scRNA-seq, WGCNA, and LASSO methodologies, DES, GREM1, MBNL1, and AEBP1 emerged as crucial core genes linked to tissue stem cell markers in endometriosis." (PMID 38115253, 2023). "By employing scRNA-seq, WGCNA, and LASSO diagnostic model development methodologies, DES, GREM1, MBNL1, and AEBP1 were identified as pivotal core genes in endometriosis that display notable associations with tissue stem cell marker genes." (PMID 38115253, 2023). "The upregulation of GREM1, a key player in early embryonic development and cyclical angiogenesis of the endometrium, was observed in both the eutopic endometrium and peripheral serum of patients diagnosed with endometriosis." (PMID 38115253, 2023). "The gathered evidence suggests that a reduction in GREM1 does affect the fertilisation rates and EDR, particularly in suboptimal cohorts, such as decrease ovarian reserved (DOR), or in cases of poor oocyte quality in women with endometriosis or polycystic ovarian syndrome." (PMID 38524634, 2024).
infertile (4 papers, 2019 to 2025). "Moreover, the expression of GREM1 is associated with fertility; infertile individuals exhibit lower levels of GREM1 expression, while increased GREM1 expression correlates with elevated FSH production." (PMID 39408808, 2024). "None of the GOIs were linked to causes of infertility, except for GREM1." (PMID 41157281, 2025). "This review included a total of 210 infertility women who underwent IVF, with studies using at least three genes of interest - HAS2, GREM1 and PTGS2 - to correlate with oocyte development competency (ODC) outcomes." (PMID 38524634, 2024).
juvenile polyposis (4 papers, 2016 to 2022). "Interestingly, the increased GREM1 expression was predicted to reduce the activity of BMP pathway, a mechanism which underlies tumorigenesis in juvenile polyposis." (PMID 28977865, 2017).
melanoma (4 papers, 2017 to 2024). A malignant, usually aggressive tumor composed of atypical, neoplastic melanocytes. "Although GREM1 expression in melanomas was not significantly higher than in other tumors, one case had the highest level of GREM1 among the tumors examined in this analysis." (PMID 28346486, 2017).
orofacial cleft (4 papers, 2016 to 2025). A disorder of facial skeleton that is characterized by cleft lip and/or cleft palate that result in feeding, speech and hearing problems caused by failures during development. "This study aims to identify potential variants in the TP63-IRF6 pathway and GREM1 for the etiology of non-syndromic orofacial cleft (NSOFC) among the Vietnamese population." (PMID 38002937, 2023). "Previous research has implicated the Gremlin-1 (GREM1) locus in human orofacial clefting." (PMID 26968009, 2016).
pancreatic ductal adenocarcinoma (4 papers, 2022 to 2025). An infiltrating adenocarcinoma that arises from the epithelial cells of the pancreas. "GREM1 has been reported to enhance TGF-β-induced extracellular matrix protein production linked to an EMT-like phenotype in pancreatic ductal carcinoma (PDAC)." (PMID 40277903, 2025). "A more recent study focused on GREM1 in pancreatic ductal carcinoma (PDAC) and demonstrated that GREM1 overexpression drove the epithelialization of mesenchymal PDAC tumors." (PMID 40277903, 2025).
sarcoma (4 papers, 2006 to 2020). A usually aggressive malignant neoplasm of the soft tissue or bone. "GREM1, which was also significantly upregulated by HE4 stable overexpression or rHE4 treatment, is overexpressed in a wide variety of cancers, including uterine cervical, lung, ovary, kidney, breast, colon, pancreas, and sarcoma, and has been shown to promote metastatic properties." (PMID 29404274, 2017).
systemic sclerosis (4 papers, 2020 to 2025). A chronic disorder, possibly autoimmune, marked by excessive production of collagen which results in hardening and thickening of body tissues. "Previous studies have reported that IL-6 regulates GREM1 in a model of the fibrotic condition, systemic sclerosis, and it is well-established that MM PCs upregulate IL-6 in stromal cell populations." (PMID 32756430, 2020).
atherosclerosis (3 papers, 2020 to 2022). A disease characterized by the build-up of fatty material and calcium deposition in the arterial wall resulting in partial or complete occlusion of the arterial lumen. "Although the function of GREM1 is unknown in TB, it has been described that in inflammatory diseases such as atherosclerosis, Gremlin 1 (GREM1), is an inhibitor of monocyte chemotaxis." (PMID 32391286, 2020).
breast tumours (3 papers, 2019 to 2023). "Our work has uncovered a strong association between high GREM1 expression in breast tumor biopsies and a poor prognosis." (PMID 31533776, 2019). "Taken together, these results suggest that CAF-derived Grem1 might play a pivotal role in promoting breast tumor progression." (PMID 31533776, 2019).
chronic pancreatitis (3 papers, 2019 to 2022). A chronic inflammatory process causing damage and fibrosis of the pancreatic parenchyma. "In line with our findings, GREM1+ fibroblasts were previously shown to be upregulated during chronic pancreatitis and PDAC99, possibly promoting disease progression through M2 macrophage polarization." (PMID 36316305, 2022). "In addition, GREM1 has been defined as a novel pro-fibrogenic factor in liver and chronic pancreatitis." (PMID 32141512, 2020).
esophageal squamous cell carcinoma (3 papers, 2021 to 2025). Esophageal squamous cell carcinoma (ESCC) is a type of esophageal carcinoma (EC) that can affect any part of the esophagus, but is usually located in the upper or middle third. "GREM1 is secreted from mesenchymal stromal cells (MSCs) and enhanced the malignancy of xenograft esophageal tumors in vivo, an effect linked to GREM1-induced EMT in esophageal squamous cell carcinoma." (PMID 40277903, 2025). "GREM1 delivered by mesenchymal stem cells (MSCs) was overexpressed in esophageal squamous cell carcinoma (ESCC), leading to enhanced EMT via TGF-β/BMP signaling." (PMID 40277903, 2025). "Several reports have identified that GREM1 amplifies TGFβ1 signaling to drive EMT in CRC and esophageal squamous cell carcinoma." (PMID 35883579, 2022). "In human esophageal squamous cell carcinoma, EMT can be promoted by GREM1 derived from mesenchymal stromal cells." (PMID 33962391, 2021).
intervertebral disc degeneration (3 papers, 2022 to 2024). "The expression of Grem1 was significantly increased in human degenerative intervertebral discs; furthermore, the expression of Grem1 positively correlated with the level of intervertebral disc degeneration." (PMID 35440754, 2022).
intestinal polyposis (3 papers, 2017 to 2025). "After treatment with antibody (UCB Ab7326), mice showed a reversion of the characteristic Vil1/Grem1 pan‐intestinal polyposis phenotype with an increase in mean survival." (PMID 40212011, 2025). "Vil1/Grem1 mice were produced, which displayed classical features of HMPS, including pronounced pan‐intestinal polyposis and lesions that phenocopy the histology of human patients, including the formation of ectopic crypts." (PMID 40212011, 2025).
intracranial aneurysm (3 papers, 2020 to 2024). "Studies have shown that miR-155-5p is upregulated in TAM-Exos and transported to smooth muscle cells (SMCs) to promote the proliferation and migration of SMCs by targeting GREM1, thereby promoting the formation of intracranial aneurysms and the activation and infiltration of TAMs." (PMID 39896803, 2024). "Likewise, miR-155-5p is confirmed to be tumorigenic, targeting GREM1 and E2F2, thereby promoting intracranial aneurysms formation and angiogenesis in pancreatic ductal adenocarcinoma." (PMID 39896803, 2024).
ischemic heart disease (3 papers, 2021 to 2024). "Still, most of these studies principally describe OPN and Grem1 expression changes in cardiomyocytes that are exposed to dilatative cardiomyopathy, acute ischemia or ischemic heart disease-induced advanced HF." (PMID 39125809, 2024). "This study is significant because modulating the expression of GREM1 can be used to promote the regenerative potential of progenitor cells and improve the efficacy of cell therapy for ischemic heart disease." (PMID 37190112, 2023). "Our results indicated that GREM1 overexpression leads to a significant decrease in mitochondrial membrane potential, suggesting that GREM1-overexpressing hMPCs may improve the efficacy of stem cell transplantation for ischemic heart disease." (PMID 37190112, 2023).
kidney damage (3 papers, 2017 to 2023). "We now show that in experimental NTS nephritis, JQ1 decreased kidney Grem-1 and Ccl8 expression, and this was associated to milder macrophage cell infiltration and the amelioration of kidney damage, therefore supporting their potential use as biomarkers of disease progression." (PMID 35215234, 2022). "For example, in an experimental mouse with folic acid-induced nephropathy, specific overexpression of Grem1 in tubules increased renal impairment, which was mainly mediated by up-regulation of local proinflammatory and pro-fibrotic factors." (PMID 37415117, 2023). "Other reports suggest that activation of VEGFR2 and NFκB inflammatory signaling plays a role in Grem1-mediated kidney damage." (PMID 28100499, 2017). "Previous studies have shown that overexpression of Grem1 could lead to aggravation of kidney damage." (PMID 37415117, 2023). "The results suggest that Grem1 may be a significant gene in the TGF-β pathway involved in nicotine-exacerbated kidney damage in DN." (PMID 37415117, 2023). "In summary, the present study confirms that Grem1 acts as a critical gene, and participation of the TGF-β signaling pathway is significant in nicotine-exacerbated kidney damage in the diabetic milieu." (PMID 37415117, 2023). "Grem1 is a critical member of the TGF-β signaling pathway, so we suspect that the TGF-β signaling pathway involves nicotine-promoting kidney damage in DN." (PMID 37415117, 2023).
lung adenocarcinoma (3 papers, 2013 to 2025). A carcinoma that arises from the lung and is characterized by the presence of malignant glandular epithelial cells. "Given its established roles in multiple cancers, it is important to explore the function of GREM1 in lung adenocarcinoma (LUAD)." (PMID 40066442, 2025). "GREM1 is a member of the aberrantly activated Hedgehog signalling pathway, and has been reported to act in an oncogenic manner in lung adenocarcinoma and can induce cell migration, invasion and proliferation." (PMID 24299561, 2013). "High expression of GREM1, encoding for the secreted factor Gremlin-1, is associated with poor overall survival in lung adenocarcinoma but not squamous cell carcinoma (PRECOG meta-Z: + 4.11 in adenocarcinoma vs − 0.75 in SCC)." (PMID 32381040, 2020).
myocardial infarction (3 papers, 2015 to 2024). Gross necrosis of the myocardium, as a result of interruption of the blood supply to the area, as in coronary thrombosis. "Since senescent cells lack the ability to contribute to tissue repair and regeneration, the decrease in senescence seen with GREM1 overexpression may allow hMPCs to be able to better aid in tissue repair when transplanted after myocardial infarction." (PMID 37190112, 2023).
neuroblastoma (3 papers, 2019 to 2025). Neuroblastoma (NB) is the most common solid, extracranial childhood tumor. "GREM1 (Gremlin 1) is a secreted glycoprotein belonging to the differential screening-selected gene in neuroblastoma (DAN) family, primarily known as an antagonist of bone morphogenetic proteins (BMPs)." (PMID 40066442, 2025). "Gremlin1 (GREM1) is a secreted glycoprotein member of the differential screening-selected gene in aberrant neuroblastoma (DAN) family of bone morphogenetic protein (BMP) antagonists, which binds to BMPs preventing their receptor engagement." (PMID 31384391, 2019). "Grem1, which is a member of the DAN (differential screening-selected gene aberrative in neuroblastoma) family of secreted BMP antagonists, selectively binds to BMP-2, -4, and -7 to exert biological functions." (PMID 35440754, 2022).
osteoporosis (3 papers, 2022 to 2025). A condition of reduced bone mass, with decreased cortical thickness and a decrease in the number and size of the trabeculae of cancellous bone (but normal chemical composition), resulting in increased fracture incidence. "The specific overexpression of Grem1 in mouse bone tissue leads to severe symptoms of osteoporosis." (PMID 35978628, 2022).
pancreatitis (3 papers, 2022 to 2025). Inflammation of the pancreas. "A total of 340 serum samples of pancreatic disease, including PDAC, low-grade malignant pancreatic neoplasm, benign pancreatic neoplasm, pancreatitis, and 132 healthy controls, were collected to detect GREM1." (PMID 36091126, 2022).
polyp (3 papers, 2021 to 2025). A usually exophytic mass attached to the underlying tissue by a broad base or a thin stalk. "GREM1 expression also exhibited a downregulation trend in our polyp specimens." (PMID 38473810, 2024). "DKK1 and DKKL1 showed a significant upregulation in polyp specimens, while WNT10B, GREM1, RSPO3, SFRP5, and GPC3 showed a downward trend." (PMID 38473810, 2024).
renal agenesis (3 papers, 2011 to 2017). Renal agenesis (RA) is a form of renal tract malformation characterized by the complete absence of development of one or both kidneys (unilateral RA or bilateral RA respectively), accompanied by absent ureter(s). "Prevalence of the complete renal agenesis in Bmp7 and Grem1-deficient and compound mutant mice at birth." (PMID 21552539, 2011). "As expected, bilateral renal agenesis was observed in about 90% of all Grem1-deficient mice at birth in the presence of either one or two functional Bmp7 alleles." (PMID 21552539, 2011). "The bilateral renal agenesis in Grem1-deficient mice is restored by additional inactivation of one Bmp4 allele." (PMID 21552539, 2011). "Genetic inactivation of one Bmp7 allele in Grem1-deficient mouse embryos does not alleviate the bilateral renal agenesis, while complete inactivation of Bmp7 restores ureteric bud outgrowth and branching." (PMID 21552539, 2011). "Genetic analysis in the mouse revealed that GREMLIN1 (GREM1)-mediated antagonism of BMP4 is essential for ureteric epithelial branching as the disruption of ureteric bud outgrowth and renal agenesis in Grem1-deficient embryos is restored by additional inactivation of one Bmp4 allele." (PMID 21552539, 2011).
sarcoidosis (3 papers, 2022 to 2025). Sarcoidosis is a multisystemic disorder of unknown cause characterized by the formation of immune granulomas in involved organs. "Examining the possible involvement of TGFB from another angle, GREM1 polymorphisms were examined by several investigators in fibrotic sarcoidosis patients." (PMID 36543347, 2022). "Significant polymorphism differences in GREM1 (gremlin 1) were found between sarcoidosis patients with and without chest radiographic abnormalities." (PMID 40217830, 2025). "Significant differences were found in the GREM1 polymorphisms between sarcoidosis patients without chest radiography abnormalities (n=116) compared to patients with fibrosis on chest radiography (n=59)." (PMID 36543347, 2022).
acute kidney injury (2 papers, 2014 to 2017). Sudden and sustained deterioration of the kidney function characterized by decreased glomerular filtration rate, increased serum creatinine or oliguria. "To determine the effect of GREM1 in renal damage in vivo, we selected mice from two lines and challenged these mice with a model of FA-mediated acute renal failure." (PMID 25036148, 2014).
carcinomas of the colon (2 papers, 2020 to 2021). "GREM1 is thought to be involved in EMT and has been shown to be overexpressed in human tumors, including carcinomas of the colon and lung." (PMID 34283070, 2021).
Hernia (2 papers, 2013 to 2019). "The potential role of GREM1 becomes further substantiated when viewed from a perspective that defects in normal wound healing and mechanical strain are frequently cited as causes of hernia formation and recurrence." (PMID 22648066, 2013). "Moreover, we have found an association between a novel gene to the hernia literature, GREM1, and incisional hernia formation." (PMID 22648066, 2013). "GREM1 was underexpressed in skin and fascia of patients with recurrent hernia compared with control subjects." (PMID 31024927, 2019).
Hyperglycemia (2 papers, 2022 to 2023). An increased concentration of glucose in the blood. "It will be interesting to generate knockout mice to remove/reduce Grem1 expression and expose them to nicotine and hyperglycemia alone or in combination." (PMID 37415117, 2023). "Among the DEGs induced by nicotine and hyperglycemia, we identified Grem1 as the most notable in all the three comparison groups (Nic + DM vs. Con, Nic + DM vs. Nic, and Nic + DM vs. DM)." (PMID 37415117, 2023). "Results from RNA-seq analysis, real-time PCR, Western blot, and immunohistochemistry analysis revealed that, compared to hyperglycemia or nicotine alone, the combination of nicotine treatment and hyperglycemia significantly increased the expression of Grem1 and worsened DN." (PMID 37415117, 2023). "Nicotine increased Grem1 expression in the glomerular and interstitium under hyperglycemia." (PMID 37415117, 2023).
Hypertension (2 papers, 2022 to 2023). The presence of chronic increased pressure in the systemic arterial system. "Age, sex, smoking, drinking, hypertension, tumor locations, distant metastasis, and tumor stages did not exhibit a significant correlation with the two GREM1 groups." (PMID 36091126, 2022).